HMGB1 (high mobility group box 1)
Diseases named in the same sentence as HMGB1 in open-access papers (continued):
Sharing a sentence is not in itself a finding about the gene and the disease.
cervical carcinoma (continued). "In this way, HMGB1 may suppress the human immune function by up-regulating Tregs, which facilitates infection and the growth of cervical-cancer cells." (PMID 24837834, 2014). "The present study demonstrated that HMGB1 might be correlated positively with Foxp3 expression and both of them were significantly enhanced in cervical cancer tissues." (PMID 24837834, 2014). "SCC-Ag was shown to have a positive relationship with HMGB1 expression, indicating that HMGB1 may acte as a biomarker for the evaluation of cervical cancer prognoses and biological behaviors." (PMID 24837834, 2014). "However, the specific and exact mechanism by which HMGB1 stimulates Tregs and its role in shifting of Th1 cells to Th2 cells in cervical cancer remains obscure." (PMID 24837834, 2014). "HMGB1, forkhead/winged helix transcription factor p3 (Foxp3), IL-2, and IL-10 protein expression was analyzed in 100 cervical tissue samples including cervical cancer, cervical intraepithelial neoplasia (CIN), and healthy control samples using immunohistochemistry." (PMID 24837834, 2014). "HMGB1 expression may activate Tregs or facilitate Th2 polarization to promote immune evasion of cervical cancer." (PMID 24837834, 2014). "Indeed, siRNA depletion of HMGB1 in human cervical carcinoma HeLa cells also resulted in a decrease in the level of RIND-EDSBs." (PMID 23977341, 2013). "previously provided evidence that SEPT9 methylation may be a biomarker for the diagnosis of cervical cancer, which functions by promoting tumorigenesis and radiation resistance of cervical cancer by targeting the HMGB1-Rb axis, and induces macrophage polarization by mediating Mir-375." (PMID 36408176, 2022). "However, whether the HMGB1/RAGE axis could affect the development of cervical cancer by regulating the inflammation is unclear." (PMID 34369271, 2021). "The limitation in our study may be that molecular functions of HMGB1 towards cervical cancer were analyzed mostly by bioinformatics analysis, the results would be diverse when divided by different criteria for grouping of HMGB1 expression and analyzed by different databases." (PMID 30962261, 2019). "RAC1 and CDC42 may be involved in the progression of cervical cancer migration induced by HMGB1." (PMID 30962261, 2019). "RAC1 and CDC42 may involve in the progression of cervical cancer migration as downstream of HMGB1." (PMID 30962261, 2019). "In conclusion, the present work suggested that miR-142 affects cervical cancer cell proliferation and invasiveness, and enhances cell apoptosis via directly targeting the expression of HMGB1, and these findings may lay a novel foundation for the promising therapy target of cervical cancer." (PMID 27829233, 2017). "However, whether Treg cells can be activated by HMGB1 in cervical cancer is unclear, and how HMGB1 can influence effector T cells needs further research." (PMID 24837834, 2014). "In addition, high levels of HMGB1 expression have been found to be a significant predictor of early prognosis in recurrent cervical SCC patients as well as an independent prognostic factor for recurrent cervical cancer outcomes." (PMID 24837834, 2014). "Thus, HMGB1 may be a useful biomarker for patient prognosis and cervical cancer prediction and treatment." (PMID 24837834, 2014). "Moreover, due to low numbers of cases, associations with tumor phenotype could not be evaluated in this study for several cancer types (non-small-cell lung cancer, cervical cancer, gastric adenocarcinoma) for which an oncogenic role of HMGB1 has previously been described." (PMID 40804938, 2025). "The expression of four different biomarkers, namely HMGB1, SCCA/SerpinB3, CEA, and CYFRA 21-1/Cytokeratin 19, in the serum of 36 cervical cancer patients was interpreted upon SDS PAGE and western blotting." (PMID 39583399, 2024).
cervical carcinoma (continued). "Our study identifies the significance of CEA, HMGB1, SCCA, and CYFRA 21-1 proteins individually and combined as biomarkers for early cervical cancer diagnosis to improve the patient's survival rate." (PMID 39583399, 2024). "Hence it may be inferred that HMGB1 expression facilitates metastasis and proliferation of cervical cancer cells, thereby serving as a valuable prognostic factor and possible biomarker for cervical cancer." (PMID 39583399, 2024). "Other reports have also indicated that ATM, PCNA, and HMGB1 are highly expressed in cervical cancer tissues, and ABCG2 is expressed at low levels in cervical cancer tissues." (PMID 35379200, 2022). "For instance, lncRNA NNT-AS1 expression was increased in CDDP-resistant cervical cancer samples and contributed to CDDP resistance in cervical cancer cells through the miR-186/HMGB1 axis." (PMID 34746018, 2021). "ALA-PDT induced the production of exosomes with high levels of HMGB1, which in turn promoted DC maturation in the peripheral blood of ALA-PDT-treated patients with cervical cancer." (PMID 32528867, 2020). "This conclusion is similar to ours that FIGO stages, lymph mode metastasis, and HMGB1 expression were independent predictors that lead to diverse OS and DFS among cervical cancer patients." (PMID 30962261, 2019). "In summary, we suggest that HMGB1 expression was independent predictors of shorter OS and DFS in patients with cervical cancer." (PMID 30962261, 2019). "Thus, HMGB1 may contribute to the cervical cancer progression via enhancing Tregs." (PMID 24837834, 2014). "In cervical cancer, serum proteins CEA, squamous cell carcinoma antigen (SCCA), high mobility group box chromosomal protein 1 (HMGB1), and CYFRA 21-1 were analyzed in 36 cervical cancer patients to identify reliable biomarkers associated with human papillomavirus (HPV) infection." (PMID 41294748, 2025). "In, 2016, an article reported that HMGB1 may be involved in the invasion, migration, and EMT of cervical cancer cells by activating the NF-kB signaling pathway through binding to RAGE." (PMID 38529373, 2024). "demonstrate that STC1-dependent immune escape from macrophage phagocytosis can be suppressed by the inhibition of competitive interaction between LNMAS and HMGB1, resulting in the abrogation of TWIST1 and STC1 chromatin accessibility, thereby suppressing cervical cancer lymph node metastasis." (PMID 38144565, 2023). "Further differential analysis of the PARP1 and HMGB1 genes revealed that PARP1 showed high expression in both the cervical cancer chip GSE9750 and the TCGA-CESC dataset, while HMGB1 only exhibited high expression in the cervical cancer chip GSE9750." (PMID 37773127, 2023). "This merits speculation that through binding to the RAGE receptor, HMGB1 may help cervical cells evade immunosuppression, and accelerate the process of “HPV infection to CIN to cervical cancer” by influencing T cell-mediated immunity." (PMID 24837834, 2014). "The data shown here suggest that HMGB1 may directly activate Tregs by binding to RAGE, which promotes IL-10 production in cervical cancer or helps to shift Th1 cells to Th2 cells and assist in tumor evasion and development." (PMID 24837834, 2014). "Despite the detection of HMGB1 in the sera of cancer patient, the clinical evaluation of HMGB1 was not performed in these cancers except for gastric and cervical cancer." (PMID 22496788, 2012). "Thus, miR-142-3p directly targets HMGA1, HMGA2, HMGB1, and HMGB3, inhibiting them through reduction of cell viability, colony formation, migration, and invasion, as well as induction of apoptosis of tumor cells, particularly cervical cancer cells." (PMID 39062899, 2024). "Moreover, SCCA, HMGB1, and CYFRA 21-1 may constitute a pivotal point of cervical oncogenesis, presenting them as prospective targets for cervical cancer prognosis." (PMID 39583399, 2024). "However, whether the HMGB1/RAGE axis regulated the inflammation and occurrence of cervical cancer remained unknown." (PMID 34369271, 2021).
cervical carcinoma (continued). "It is speculated here that HMGB1 might help tumor cells evade immune surveillance and could be a useful negative prognostic indicator of cervical carcinoma." (PMID 24837834, 2014). "In our study, a negative correlation between HMGB1 and SEPT9 expression was identified in cervical cancer by immunohistochemical staining." (PMID 31426855, 2019).
osteosarcoma (59 papers, 2013 to 2025). A usually aggressive malignant bone-forming mesenchymal neoplasm, predominantly affecting adolescents and young adults. "High expressions of both lncR-C3orf35 and HMGB1 were significantly associated with poor overall survival of osteosarcoma patients." (PMID 33015161, 2020). "Through KM analysis, the lncR-C3orf35/HMGB1 pair was found to be associated with the overall survival of osteosarcoma patients." (PMID 33015161, 2020). "Our study showed that high HMGB1 expression was associated with metastasis and immune cell infiltration of osteosarcoma, which was consistent with previous studies." (PMID 33015161, 2020). "The results indicated that macrophage infiltration in osteosarcoma tissue was associated with lncR-C3orf35/HMGB1 expression." (PMID 33015161, 2020). "Kaplan-Meier survival analysis showed that lncR-C3orf35 and HMGB1 were associated with poor prognosis of osteosarcoma patients." (PMID 33015161, 2020). "Previously, it was reported that overexpression of HMGB1 is associated with tumorigenesis, invasion, and metastasis of osteosarcoma, and its expression can be regulated by multiple miRNAs in diverse cancers." (PMID 29899164, 2018). "The main functions of HMGB1 are related to DNA-associated processes, including replication, translation, and repair; however, its role within osteosarcoma development may be related to the inhibition of osteosarcoma cell migration and proliferation." (PMID 35011442, 2021). "lncR-C3orf35 and HMGB1 were associated with poor prognosis of osteosarcoma patients." (PMID 33015161, 2020). "Dysregulation of HMGB1 is linked to several types of cancer including osteosarcoma." (PMID 29899164, 2018). "HMGB1 overexpression has been associated with resistance to cisplatin treatment in human cancer cervical cells, non-small-cell lung cancer, neuroblastoma and osteosarcoma, by mechanisms of cell autophagy, a fundamental lysosomal process that confers stress tolerance and inhibits apoptosis." (PMID 36614297, 2023). "Hence, lncR-C3orf35/HMGB1 expression was associated with immune cell infiltration in osteosarcoma." (PMID 33015161, 2020). "Another study demonstrated that circ-LRP6 regulates the miR-141-3p/HDAC4/HMGB1 axis to contribute to osteosarcoma progression." (PMID 40696350, 2025). "M2 TAMs induce high mobility group box 1 (HMGB1) expression in osteosarcoma cells, promoting migration and invasion, while HMGB1 further enhances M2 polarization." (PMID 41383602, 2025). "Although dedicated clinical trials for osteosarcoma remain limited, existing experimental data provide a theoretical basis for targeting HMGB1 in the treatment of osteosarcoma." (PMID 41296391, 2025). "Previous studies have shown that patients with osteosarcoma (OS) who have high HMGB1 expression tend to have lower survival rates and a poorer prognosis." (PMID 41296391, 2025). "Digitoxin and digoxin, foxglove (Digitalis purpurea)-derived cardenolides, upregulate ICD-related molecules such as DAMPs (HSP90, CALR, and HMGB1) in osteosarcoma cells." (PMID 39759512, 2024). "For example, miR-505-3p was shown to inhibit osteosarcoma tumorigenesis by targeting HMGB1 directly." (PMID 38970074, 2024). "Considering the Most Cited Papers, Most Global Cited Papers, Most Co-Cited References, and Most Local Cited References, “HMGB1 Promotes Drug Resistance in Osteosarcoma” emerges as a seminal work in the discipline." (PMID 39655055, 2024). "This research illuminates the role of the DNA-binding protein HMGB1 in imparting chemotherapy resistance in osteosarcoma, positioning it as a pivotal target for improving therapeutic results." (PMID 39655055, 2024). "This study demonstrates that the DNA-binding protein HMGB1 induces chemoresistance in osteosarcoma by promoting autophagy, offering a novel target for therapy improvement." (PMID 39655055, 2024).
osteosarcoma (continued). "It identifies HMGB1’s pivotal role in fostering chemoresistance in osteosarcoma by promoting autophagy, positioning it as an innovative target for enhancing treatment efficacy." (PMID 39655055, 2024). "Significantly, Zhang Yuan is acknowledged as the leading expert in this area, with “HMGB1 Promotes Drug Resistance in Osteosarcoma” acclaimed as the most consequential paper." (PMID 39655055, 2024). "Subsequent influential works include “HMGB1 Promotes Drug Resistance in Osteosarcoma”, the third most co-cited article, renowned for its extensive citations within this research domain." (PMID 39655055, 2024). "KLF4 was shown to contribute to chemoresistance in osteosarcoma partially through regulation of the high-mobility group box 1 (HMGB1)." (PMID 39685635, 2024). "As one of the three anticancer drugs, doxorubicin triggers the upregulation of HMGB1 in osteosarcoma cells." (PMID 38064181, 2023). "In turn, HMGB1, a DNA chaperone, was connected with the progression of different cancers and apoptosis, chemoresistance, and proliferation of osteosarcoma cells." (PMID 37511619, 2023). "MGN also enhanced the CDDP sensitivity of MG-63 and U-2 osteosarcoma cells via the suppression of HMGB1/NF-κB signaling." (PMID 37958494, 2023). "Circ-LRP6 sponged miR-141-3p, which resulted in higher expression of two targets of this miRNA, HDAC4 and HMGB1, and promoted the proliferation, migration, and invasion of osteosarcoma cells." (PMID 37511619, 2023). "As a key regulator of autophagy, HMGB1 promotes drug resistance of a number of cancers including osteosarcoma, lung adenocarcinoma, and leukemia by activating protective autophagy following pharmacotherapy." (PMID 35211417, 2022). "In our study, the expression of HMGB1 is higher in normal tissues than that in osteosarcoma from TARGET dataset." (PMID 36204682, 2022). "They found that HMGB1 was targeted by miR-22, miR-218, miR-26a, miR-34a, miR-129-5p, and miR-142-3p to sensitize osteosarcoma, endometrial carcinoma, melanoma, retinoblastoma, breast cancer, NSCLC to chemotherapeutic agents through inhibiting autophagy." (PMID 35211417, 2022). "On the other hand, the macrophage population first decreases and then increases during osteosarcoma progression, while necrotic cells, HMGB1, along with the cytokine groups μ1 and μ2 increase in population as cancer cells grow." (PMID 34068946, 2021). "The expression of HMGB1 in osteosarcoma tissues was significantly higher than that in normal bone tissues." (PMID 33140586, 2021). "In chemotherapy for osteosarcoma, HMGB1 binds to the autophagy regulator Beclin1 and regulates the formation of the Beclin1–PI3KC3 complex, which induces autophagy to increase drug resistance." (PMID 33140586, 2021). "In this study, we observed the expression of miR‐505 and HMGB1 and analyzed their clinical values in osteosarcoma." (PMID 32348630, 2020). "To date, there are limited studies focusing on the mechanisms of miR‐505 and HMGB1 with respect to osteosarcoma." (PMID 32348630, 2020). "Relationships among miR‐505, HMGB1, and clinical pathological characteristics of patients with osteosarcoma." (PMID 32348630, 2020). "Extracellular HMGB1 protein results in higher osteosarcoma cell proliferation, migration, and osteogenic differentiation." (PMID 33015161, 2020). "Further analysis showed that patients with osteosarcoma metastasis expressed higher levels of lncR-C3orf35 and HMGB1 compared to metastasis-free patients." (PMID 33015161, 2020). "Accordingly, the data suggested that the regulatory role of HULC was through the miR-372-3p/HMGB1 signalling pathway to promote the development of osteosarcoma cells." (PMID 32188407, 2020). "We further confirmed differences in gene expression by microarray data and qRT-PCR, which supported the expression of the lncR-C3orf35/miR142-3p/HMGB1 axis in osteosarcoma." (PMID 33015161, 2020).
osteosarcoma (continued). "In one study, doxorubicin, cisplatin, and methotrexate were found to upregulate expression of HMGB1 mRNA in osteosarcoma cell lines MG-63, Saos-2, and U2-OS." (PMID 32961800, 2020). "Further studies are needed to explore the biological functions of the lncR-C3orf35/miR142-3p/HMGB1 axis in osteosarcoma." (PMID 33015161, 2020). "Further rescue experiments showed that HULC promoted proliferation and metastasis in osteosarcoma via regulation of the miR-372-3p/HMGB1 signalling axis." (PMID 32188407, 2020). "The miR-410-3p mimic inhibited the EMT of osteosarcoma cells, which was restored by an upregulation of HMGB1." (PMID 33182753, 2020). "It was found that overexpression of mir‐505 inhibited the expression of HMGB1 and restricted the growth of osteosarcoma tumor cells." (PMID 32348630, 2020). "The expression of the lncR-C3orf35/miR142-3p/HMGB1 axis was validated by quantitative real-time PCR (qRT-PCR) in osteosarcoma cells." (PMID 33015161, 2020). "In conclusion, miR‐505 overexpression has the potential to be used as a clinical index and target because it inhibits HMGB1 expression as well as the proliferation and invasion capacity of osteosarcoma cells, while also increasing the apoptosis rate." (PMID 32348630, 2020). "Second, there was an insufficient focus on the signal channel to further analyze the relationships among miR‐505, HMGB1, and the signal channel as well as its impact on the biological functions of osteosarcoma cells, leading to incomplete results." (PMID 32348630, 2020). "Another study demonstrated that chemotherapy resistance in osteosarcoma cell lines is dependent on both HMGB1 and autophagy." (PMID 32961800, 2020). "The best cutoff value, sensitivity, and specificity were determined according to the ROC of osteosarcoma diagnosis based on serum miR‐505 and HMGB1 expression." (PMID 32348630, 2020). "It has been demonstrated that MGN inhibits the malignant phenotypes and increases the CDDP sensitivity of osteosarcoma cells via modulating the miR-410-3p/HMGB1/NF-κB pathway." (PMID 33182753, 2020). "Accordingly, it was suggested that miR‐505 and HMGB1 participate in the development and progression of osteosarcoma, and this was further validated through cytobiological tests." (PMID 32348630, 2020). "Several genes in the network were shown to be dysregulated and to function as oncogenes or tumor suppressors in osteosarcoma, such as HMGB1 and miR-142-3p." (PMID 33015161, 2020). "lncR-C3orf35 (p < 0.0001) and HMGB1 (p = 0.0003) were overexpressed in the osteosarcoma cell line SASJ-2 compared to the human osteoblast cell line hFOB 1.19." (PMID 33015161, 2020). "It was reported that hsa-miR-22-3p inhibits osteosarcoma cell proliferation and migration through targeting HMGB1." (PMID 29899164, 2018). "We used miR-1284 mimics and negative control (miR-NC) to determine the effect of overexpressed miR-1284 on the expression of HMGB1 in human osteosarcoma cell lines, MG-63, and U2OS." (PMID 29899164, 2018). "In the present study, we showed that miR-1284 was down-regulated in osteosarcoma tissues where HMGB1 is overexpressed, indicating a reverse correlation between miR-1284 and HMGB1." (PMID 29899164, 2018). "In conclusion, miR-1284 can function as a new regulator to inhibit osteosarcoma cell proliferation and migration by targeting HMGB1." (PMID 29899164, 2018). "In the present study, we aim to investigate potential role of miR-1284 in osteosarcoma cell growth and migration through regulation of HMGB1." (PMID 29899164, 2018). "miR-22 suppressed osteosarcoma cell proliferation and migration by targeting HMGB1 and inhibiting HMGB1-mediated autophagy." (PMID 28882183, 2017). "Chemotherapy-induced HMGB1 expression in osteosarcoma cells promoted autophagy through controlling the formation of the Beclin 1-phosphatidylinositol 3-kinase class 3 (PI3KC3) complex to inhibit apoptosis and increase drug resistance." (PMID 25622595, 2015).